SHH (sonic hedgehog signaling molecule)
Diseases named in the same sentence as SHH in open-access papers (continued):
Sharing a sentence is not in itself a finding about the gene and the disease.
bacterial infection (1 paper, 2018). "Rather, the direct contact between adjacent cells expressing SHH ligand and the correspondent receptors, respectively, is likely critical for effective activation of SHH signaling in the SHH responding cells following systemic bacterial infection." (PMID 29535725, 2018). "To further verify the role of SHH–Gli1 signaling in the activation of primitive hematopoietic precursor cells during the granulopoietic response to serious bacterial infection, we employed an in vivo model of mice with Gli1 deletion." (PMID 29535725, 2018). "At the present time, nevertheless, it remains elusive if SHH–Gli1 signaling participates in the regulation of primitive hematopoietic precursor cell activation and reprograming in host defense against serious bacterial infection." (PMID 29535725, 2018). "This increase in cell expression of SHH in response to systemic bacterial infection was validated by ELISA analysis." (PMID 29535725, 2018). "Our results from the current investigation demonstrate that activation of SHH–Gli1 signaling plays a pivotal role in mediating primitive hematopoietic precursor cell activation during the granulopoietic response to serious bacterial infection." (PMID 29535725, 2018). "In the current study, we examined the role of SHH–Gli1 signaling in the activation of primitive hematopoietic precursor cells during the granulopoietic response to system bacterial infection." (PMID 29535725, 2018). "Our results indicate that SHH signaling is critically important in the regulation of hematopoietic stem/progenitor cell activation and reprogramming during the granulopoietic response to serious bacterial infection." (PMID 29535725, 2018). "Further investigation on the alteration of SHH expression by these niche cell types will be helpful for further elucidating their possible involvement in the regulation of SHH signaling in hematopoietic precursor cells during the host response to systemic bacterial infection." (PMID 29535725, 2018). "This increase in Gli1 expression in marrow lin+ cells appears to imply that the activation of the SHH signaling may also participate in the regulation of functional activities in lin-committed hematopoietic progenitors during the granulopoietic response to the systemic bacterial infection." (PMID 29535725, 2018).
cardiovascular diseases (1 paper, 2018). "Results from these experiments showed downstream HH signaling proteins such as PTCH1, SMO, GLI 1, GLI 2 and GLI 3 to be functionally impaired, indicating impairment of SHH signaling pathway in cardiovascular diseases." (PMID 30301174, 2018). "As a promising therapeutic tool, the possibility of using the SHH signaling pathway for the activation of EPCs in patients suffering from cardiovascular diseases is further explored." (PMID 30301174, 2018). "As endothelial cells are the major cellular component of the cardiac tissue, together with SHH molecules, they could be therapeutically exploited to benefit patients suffering from cardiovascular diseases." (PMID 30301174, 2018). "The canonical and non-canonical SHH signaling pathways in EPCs and endothelial cells (ECs) related to homeostasis, SHH signal transmission by extracellular vesicles (EVs) or exosomes containing single-strand non-coding miRNAs and impaired SHH signaling in cardiovascular diseases are discussed." (PMID 30301174, 2018).
gastrointestinal tumors (1 paper, 2014). "The hypomethylation of HHIP, the inhibitor of SHH, has been observed in gastrointestinal tumors." (PMID 25013484, 2014).
SHH also shares sentences with these, for which no sentence is quoted: cerebellar tumor (3 papers); chondrosarcoma (3); holoprosencephaly 3 (3); idiopathic pulmonary fibrosis (3); Insulin resistance (3); multiple myeloma (3); skin cancer (3); acute myocardial infarction (2); Adamantinomatous Craniopharyngioma (2); Anxiety (2); autosomal dominant polycystic kidney disease (2); colorectal tumor (2); exomphalos (2); Fanconi anaemia (2); hypopituitarism (2); Keratocystic odontogenic tumor (2); schizencephaly (2); schizophrenia (2); -dependent (1); acral melanoma (1); acute lung injury (1); acute lymphoblastic leukemia (1); adenoid cystic carcinoma (1); adenomatoid odontogenic tumor (1); adrenocortical carcinoma (1); adrenocortical tumors (1); Alström syndrome (1); Alzheimer disease (1); anaplastic large cell lymphoma (1); aniridia (1).
A further 94 diseases each share a sentence with SHH in 1 paper.